PRDX5 (peroxiredoxin 5)
Diseases named in the same sentence as PRDX5 in open-access papers (continued):
Sharing a sentence is not in itself a finding about the gene and the disease.
neurodegenerative disease (2 papers, 2024 to 2025). A disorder of the central nervous system characterized by gradual and progressive loss of neural tissue and neurologic function. "In neurodegenerative diseases, Prdx5 has been linked to changes in redox homeostasis and to increased iron overload-induced neuronal death." (PMID 41488750, 2025).
PRDX5 also shares sentences with these, for which no sentence is quoted: rheumatoid arthritis (10 papers); malaria (7); melanoma (6); bacterial infection (4); pancreatic cancer (4); triple-negative breast carcinoma (4); cardiac hypertrophy (3); cardiovascular disease (3); myeloma (3); non-small cell lung carcinoma (3); cervical cancer (2); chlamydial diseases (2); Crohn disease (2); diabetes (2); glioblastoma (2); glioma (2); Hepatic fibrosis (2); Hepatic steatosis (2); leukemia (2); neuroblastoma (2); neurological disease (2); selenium deficiency (2); Sepsis (2); tuberous sclerosis (2); viral infection (2); Acanthamoeba infections (1); acute myeloid leukemia (1); adenocarcinoma (1); age (1); alcoholic hepatitis (1).
A further 65 diseases each share a sentence with PRDX5 in 1 paper.